RSPH3 (radial spoke head 3)
Description:
Functions as part of axonemal radial spoke complexes that play an important part in the motility of sperm and cilia (By similarity). Functions as a protein kinase A-anchoring protein that scaffolds the cAMP-dependent protein kinase holoenzyme. May serve as a point of convergence for MAPK and PKA signaling in cilia.
Synonyms: RSHL2; RSP3; dJ111C20.1; CILD32
Gene: Protein-coding gene on chromosome 6 (158,970,084 to 159,000,202, reverse strand). Ensembl gene ENSG00000130363.
Subcellular location: Cytoplasm, cytoskeleton, cilium axoneme; Cytoplasm, cytoskeleton, flagellum axoneme
Subcellular location (Human Protein Atlas): Annulus; Flagellar centriole; Mid piece; Plasma membrane; Cytosol
Genetic constraint (gnomAD): Loss-of-function variants: 14 observed, 27.91 expected, observed/expected ratio (o/e) 0.5, 90% interval 0.33 to 0.78. The upper end of that interval is the gene's LOEUF score, 0.78, which puts it in group 3 of 6, group 1 being the genes least tolerant of losing a copy. Missense variants: 385 observed, 406.13 expected, observed/expected ratio (o/e) 0.95, 90% interval 0.87 to 1.03. Synonymous variants: 135 observed, 146.93 expected, observed/expected ratio (o/e) 0.92, 90% interval 0.8 to 1.06.
Gene-disease validity (ClinGen):
ClinGen rates the evidence that RSPH3 causes each of these diseases.
primary ciliary dyskinesia 32 (autosomal recessive): Definitive.
Homologues: Orthologues: chimpanzee RSPH3 (99% identical), macaque RSPH3 (87% identical), dog RSPH3 (79% identical), pig RSPH3 (75% identical), guinea pig RSPH3 (72% identical), rat Rsph3 (69% identical), mouse Rsph3b (69% identical), mouse Rsph3a (69% identical), tropical clawed frog rsph3 (56% identical), rabbit RSPH3 (55% identical), zebrafish rsph3 (49% identical), Drosophila melanogaster Rsph3 (32% identical).
Diseases named in the same sentence as RSPH3 in open-access papers:
RSPH3 is named in the same sentence as 13 diseases in open-access papers, as found by Europe PMC text mining. Sharing a sentence is not in itself a finding about the gene and the disease. The quoted sentences say what the papers report.
male infertility (3 papers, 2023 to 2025). The inability of the male to effect fertilization of an ovum after a specified period of unprotected intercourse. "Although the RSPH3 gene is abundantly expressed in testicular tissue, the phenotype of PCD-associated male infertility caused by the defect in this ciliopathy-related gene has been rarely described." (PMID 37670815, 2023). "Intersection of genes from transcriptomic studies with genes with identified rare variants revealed a total of 7 genes linked with male infertility phenotype (CYP11A1, CYP17A1, RSPH3, TSGA10, AKAP4, CCIN, NDNF)." (PMID 37670815, 2023).
primary ciliary dyskinesia (3 papers, 2022 to 2025). A rare, genetically heterogeneous, primarily respiratory disorder characterized by chronic upper and lower respiratory tract disease. "Mutations in the RSPH3 gene have been associated with primary ciliary dyskinesia in humans, a disease characterized by defects in axial filaments in mobile cilia and sperm flagella." (PMID 39943208, 2025). "RSPH3 biallelic variants represent a recurrent genetic cause of Primary ciliary dyskinesia (PCD) in human." (PMID 37670815, 2023). "In addition, the gene RSPH3 causing primary ciliary dyskinesia is also further examined." (PMID 35524249, 2022). "In addition, the association of RSPH3 (the gene is related to primary ciliary dyskinesia) is observed in non-obese asthma." (PMID 35524249, 2022).
infertile (2 papers, 2023). "Some of the male patients carrying RSPH1 and RSPH3 mutations were infertile." (PMID 38091523, 2023).
breast carcinoma (1 paper, 2022). "Among these six genes, five were hypermethylated (GABRA5, ZIC5, GRAMD4, RSPH3, and VCAN), and one was hypomethylated (CSMD1) in breast cancer samples of cases compared to controls." (PMID 36627894, 2022).
situs inversus (1 paper, 2022). A congenital condition in which there is complete right-to-left reversal of the position of the major thoracic and abdominal organs (that is, they are arranged in a mirror image of the normal positioning). "Normal visceral placement is driven by the dynein of nodal cilia, so patients with gene mutations encoding non-dynein structural components such as RSPH1, RSPH3, and HYDIN have not been reported for situs inversus." (PMID 36583018, 2022).
RSPH3 also shares sentences with these, for which no sentence is quoted: infection (3 papers); melanoma (2); asthenozoospermia (1); asthma (1); ciliopathies (1); genetic disease (1); Obesity (1); tumor (1).